SELENOO (selenoprotein O)
Description:
Catalyzes the transfer of adenosine 5'-monophosphate (AMP) to Ser, Thr and Tyr residues of target proteins (AMPylation). May be a redox-active mitochondrial selenoprotein which interacts with a redox target protein.
Synonyms: SelO
Tractability: PROTAC: ubiquitination databases record sites on it.
Gene: Protein-coding gene on chromosome 22 (50,201,011 to 50,217,616, forward strand). Ensembl gene ENSG00000073169.
Subcellular location: Mitochondrion
Subcellular location (Human Protein Atlas): Mitochondria; Mitotic chromosome
Gene Ontology:
Molecular function: AMPylase activity; protein binding
Biological process: protein adenylylation
Cellular component: chromosome; mitochondrion
Genetic constraint (gnomAD): Loss-of-function variants: 74 observed, 52.49 expected, observed/expected ratio (o/e) 1.41, 90% interval 1.17 to 1.71. The synonymous counts are far from expectation, so gnomAD's model fits this gene poorly and the ratio says little. Missense variants: 1,144 observed, 873.3 expected, observed/expected ratio (o/e) 1.31, 90% interval 1.25 to 1.38. Synonymous variants: 540 observed, 393.18 expected, observed/expected ratio (o/e) 1.37, 90% interval 1.28 to 1.48.
Homologues: Orthologues: chimpanzee SELENOO (99% identical), dog SELENOO (85% identical), pig SELENOO (84% identical), mouse Selenoo (81% identical), rat Selenoo (81% identical), guinea pig SELENOO (80% identical), macaque SELENOO (76% identical), rabbit SELENOO (55% identical), zebrafish selenoo1 (55% identical), zebrafish selenoo2 (53% identical), tropical clawed frog trabd (50% identical).
Diseases named in the same sentence as SELENOO in open-access papers:
SELENOO is named in the same sentence as 11 diseases in open-access papers, as found by Europe PMC text mining. Sharing a sentence is not in itself a finding about the gene and the disease. The quoted sentences say what the papers report.
alcohol abuse (1 paper, 2018). The use of alcoholic beverages to excess, either on individual occasions ("binge drinking") or as a regular practice. "Interestingly, the variants identified in EPS8L3 (rs148185176), MYH7, CRX (rs139340178), and SELENOO, were also present in two relatives with alcohol abuse (individuals 6 and 18)." (PMID 30379966, 2018).
HIV-1 infection (1 paper, 2022). The type species of lentivirus and the etiologic agent of acquired immunodeficiency syndrome (AIDS). "We monitored the expression of five selenoproteins, namely GPX4, GPX1, SELENOO, TXNRD1 and SELENOS, in response to HIV-1 infection at various time points and in cellular protein extracts." (PMID 35163318, 2022).
steatosis (1 paper, 2021). Increased lipid within the cytoplasm of cells. "Similarly, four out the five genes with lower expression in steatosis also had lower expression in NASH (SELENOO, SELENON, DIO3, and TXNRD3) compared to HC." (PMID 34869521, 2021). "Amongst the 13 genes, eight (DIO1, GPX2, SEPHS2, SELENOK, SELENOS, SELENOT, SELENOF, and SELENOW) had higher, and five (DIO3, GPX1, SELENON, SELENOO, and TXNRD3) had lower expression in steatosis." (PMID 34869521, 2021). "Of these genes, 11 coded for selenoproteins of which four genes had lower expression (SELENON, SELENOO, GPX1, and TXNRD3) and seven genes had higher expression (SELENOK, SELENOS, SELENOW, GPX2, GXP3, DIO1, and SEPHS2) in steatosis." (PMID 34869521, 2021).
SELENOO also shares sentences with these, for which no sentence is quoted: melanoma (2 papers); tumor (2); breast tumor (1); cancer (1); leprosy (1); lung carcinoma (1); Pleural effusion (1); selenium deficiency (1).